PRMT1 (protein arginine methyltransferase 1)
Diseases named in the same sentence as PRMT1 in open-access papers (continued):
Sharing a sentence is not in itself a finding about the gene and the disease.
neuroblastoma (continued). "The results confirmed the cellular senescence in the neuroblastoma cells after the PRMT1 expression was knocked down." (PMID 30741995, 2019). "First, we observed a strong correlation between MYCN and PRMT1 protein levels in primary neuroblastoma tumors." (PMID 27571165, 2016). "Third, depletion of PRMT1 through siRNA knockdown reduced neuroblastoma cell viability and MYCN expression." (PMID 27571165, 2016). "Our results highlight the potential of PRMT1 as a drug target for neuroblastoma and other cancers driven by the MYCN oncoprotein." (PMID 27571165, 2016). "The gene protein arginine methyltransferase 1 (PRMT1) was identified as a MYCN direct target gene and high levels of PRMT1 mRNA correlated with poor prognosis in a series of 88 primary neuroblastoma tumors." (PMID 27571165, 2016). "High PRMT1 expression levels are correlated with poor prognosis of neuroblastoma." (PMID 39826691, 2025). "Moreover, ATF5 is a down-stream effector of protein arginine methyltransferase 1 (PRMT1), which is an essential regulator of neuroblastoma cell survival." (PMID 35806136, 2022). "Furthermore, a diamidine class of PRMT1 inhibitors exhibited anti-neuroblastoma efficacy both in vitro and in vivo." (PMID 32415090, 2020). "Here, we demonstrate a critical role for PRMT1 in neuroblastoma cell survival." (PMID 32415090, 2020). "Whether and how PRMT1 plays differential roles for survival of neuroblastoma spheres versus cell lines awaits further investigation." (PMID 32415090, 2020). "Taken together, these findings indicate that PRMT1 may play a general role for neuroblastoma cell proliferation." (PMID 32415090, 2020). "We report here, to our knowledge, PRMT1 as a novel regulator of ATF5 in neuroblastoma." (PMID 32415090, 2020). "Taken together, these results suggest that PRMT1 inhibition with diamidine compounds may be an effective therapeutic strategy for neuroblastoma." (PMID 32415090, 2020). "PRMT1 depletion decreased the ability of murine neuroblastoma sphere cells to grow and form spheres, and suppressed proliferation and induced apoptosis of human neuroblastoma cells." (PMID 32415090, 2020). "PRMT1 promotes cell survival through epigenetic activation of the prosurvival factor ATF5, thus providing a new mechanistic link between overexpression of PRMT1 and compromised apoptotic pathway, a malignant phenotype characteristic of a large number of cancers, including neuroblastoma." (PMID 32415090, 2020). "Importantly, our studies indicate that regulation of MAPK kinase activity, separate from apoptosis pathway, is among the most significantly regulated effects of PRMT1 depletion on neuroblastoma cells." (PMID 32415090, 2020). "Here, we reveal a novel role of PRMT1 in promoting neuroblastoma cell survival." (PMID 32415090, 2020). "As such, we aimed to study PRMT1 in neuroblastoma, a tumor derived from the neural crest cells." (PMID 30741995, 2019). "Taken together, these data suggest that targeting PRMT1-mediated post-translational modification of proteins may provide a compelling therapeutic strategy for cancers, including neuroblastoma." (PMID 27571165, 2016). "Furthermore, PRMT1-mediated survival pathway is critical in neuroblastoma." (PMID 39826691, 2025). "Our results suggest that PRMT1 may represent an attractive, druggable target for neuroblastoma." (PMID 32415090, 2020). "Together, these data confirm a critical role of PRMT1 activity for the initiation and progression of neuroblastoma tumor in a well-established preclinical mouse model and suggest that inhibition of PRMT1 activity may represent a promising strategy for neuroblastoma." (PMID 32415090, 2020). "Finally, we examined whether suppression of PRMT1 activity could block neuroblastoma tumor initiation." (PMID 32415090, 2020). "Therefore, it is tempting to speculate that ATF5 may act as a general downstream effector of PRMT1-mediated survival signaling in neuroblastoma." (PMID 32415090, 2020).
neuroblastoma (continued). "The study has shown that inhibition of protein arginine methyltransferases 1 (PRMT1) induces apoptosis of human neuroblastoma cells and that ATF5 acts as a downstream effector of PRMT1-mediated survival signaling." (PMID 38014922, 2023). "Depletion of PRMT1 in this report reduced the expression of MYCN and cell viability in primary neuroblastoma tumors." (PMID 33440687, 2021). "Our previous work demonstrated critical roles of PRMT1 and PRMT5 for neuroblastoma cell growth in part through arginine methylation of MYCN and subsequent enhancement of its stability." (PMID 32415090, 2020). "Here we provide several lines of evidence demonstrating PRMT1 as a novel regulator of MYCN and implicating PRMT1 as a potential therapeutic target in neuroblastoma pathogenesis." (PMID 27571165, 2016). "In this study, we identify PRMT1 as a novel essential regulator of MYCN and its level as a significant independent prognostic marker in primary neuroblastoma tumors." (PMID 27571165, 2016). "We then examined the subcellular localization of endogenous FUS/TLS and PRMT1 in HEK293 and neuroblastoma SH-SY5Y cells by immunofluorescence assay." (PMID 23152885, 2012). "Previous results showed that PRMT1 regulated MYCN expression in neuroblastoma, and down-regulation of PRMT1 induced the senescence of non-MYCN amplified neuroblastoma cells." (PMID 32593299, 2020). "MYCN-amplified tumors exhibited high levels of PRMT1 and PRMT5; knockdown of either PRMT1 or PRMT5 led to downregulation of MYCN and suppression of cell growth, suggesting a dependence of MYCN-amplified neuroblastoma on PRMTs3,4." (PMID 32415090, 2020). "We then depleted PRMT1 in two independent MYCN-non-amplified neuroblastoma cell lines SK-N-AS and SH-EP1, and observed similar suppression of cell proliferation in both cell lines." (PMID 32415090, 2020). "PRMT1 siRNA knockdown reduces MYCN expression and neuroblastoma cell viability." (PMID 30741995, 2019). "In this study, we investigated the effects of low PRMT1 levels on a non-MYCN amplified neuroblastoma SK-N-SH cell line." (PMID 30741995, 2019). "We aimed to knock down PRMT1 expression in a neuroblastoma cell line that is not MYCN-amplified or overexpressed to study the effects of low PRMT1 levels in these cells." (PMID 30741995, 2019). "Conversely, previous studies revealed that PRMT1 is positively correlated with MYCN in a large Kocak dataset with 476 patients with non-MYCN classified neuroblastoma." (PMID 30741995, 2019). "We propose that PRMT1 may exert its functions through multiple and non-mutually exclusive mechanisms to stimulate neuroblastoma cell growth." (PMID 32415090, 2020). "Indeed, we found that the currently available PRMT5 inhibitors, such as EPZ015666 were not able to recapitulate the sensitivity of human neuroblastoma cells in response to depletion of PRMT1 or PRMT5 (data not shown)." (PMID 32415090, 2020). "Interestingly, these compounds exhibited similar potency in MYCN-amplified versus non-amplified neuroblastoma cell lines, which is consistent with a similar reduction of cell proliferation upon PRMT1 silencing regardless of MYCN amplification." (PMID 32415090, 2020). "However, we found that the PRMT1 expression levels were not correlated with MYCN levels in a cohort of patients with non-MYCN-amplified neuroblastoma." (PMID 30741995, 2019).
neuroblastoma (continued). "Thus, the roles of PRMT1 in patients with non-MYCN-amplified neuroblastoma should be further investigated." (PMID 30741995, 2019). "However, the analyses of the Seeger dataset with 102 patients with non-MYCN amplified neuroblastoma using the R2 platform showed unfavorable prognosis in patients with low PRMT1 expression levels." (PMID 30741995, 2019). "The dual inhibition of PRMT1 and PRMT5 has not yet been evaluated in neuroblastoma." (PMID 32415090, 2020). "In neuroblastomas with MYCN amplification or high MYCN levels without MYCN amplification, the positive regulatory loop of the MYCN-PRMT1 axis may promote a MYCN-driven oncogenic program whereas PRMT1-mediated activation of ATF5 may lead to enhanced survival." (PMID 32415090, 2020).
pancreatic cancer (16 papers, 2020 to 2025). "PRMT1 expression is increased in patients with pancreatic cancer, and higher expression is associated with poorer prognosis." (PMID 36902253, 2023). "In this study, we showed that the depletion of PRMT1 significantly inhibits the proliferation of pancreatic cancer cells, including PANC-1 and MiaPaca-2." (PMID 40675804, 2025). "Similar results were also observed in PANC-1 cell lines, suggesting that endogenous human PRMT1 exists as a higher-order oligomer in both HeLa cells and the human pancreatic cancer cell line PANC-1." (PMID 40675804, 2025). "In pancreatic cancer, PRMT1 expression increases after gemcitabine (GEM) treatment, with acquired chemoresistance promoted by delayed clearance of DNA damage markers (e.g., γ H2AX and RPA32), prolonged S‐phase arrest, and improved damage repair mechanisms." (PMID 41256732, 2025). "By mediating ADMA of substrate proteins, the post-translational modification enzyme PRMT1 plays a significant role in pancreatic cancer." (PMID 38326807, 2024). "In an experimental setting, PRMT1 promotes growth of pancreatic cancer cells in vitro and in vivo via enhancing the ß-catenin level." (PMID 38612768, 2024). "PRMT1 can bind to the β-catenin promoter region, increasing the expression of the β-catenin protein in pancreatic cancer cells." (PMID 36902253, 2023). "Recently, in pancreatic cancer, mRNA regulators/RNA-binding splicing factors were identified as methylation targets of PRMT1 (Protein Arginine Methyl Transferase 1)." (PMID 35817785, 2022). "In summary, our findings reveal the critical role of PRMT1 in pancreatic tumor maintenance to support a complex network of mechanisms that ensure cell cycle progression and genomic stability." (PMID 34330913, 2021). "Curiously, the addition of PRMT1 to PRMT5 inhibition in a pancreatic cancer cell line induces a synergistic increase in >2400 novel ASEs compared with PRMT5 or PRMT1 inhibitor alone." (PMID 34680285, 2021). "Furthermore, aberrant expression of PRMT1 has been documented in several cancer types, including breast, colorectal, and pancreatic cancers." (PMID 40675804, 2025). "In cancer, PRMT1 expression predicts sensitivity to platinum-based chemotherapy in patients with ovarian and pancreatic cancers, and PRMT1 inhibition reduces the clonogenic growth of cancer cells exposed to low doses of cisplatin, sensitizing them to apoptosis." (PMID 41053315, 2025). "Similarly, different oligomeric states of PRMT1-expressing PDAC cells were established from PRMT1-depleted human pancreatic cancer cell lines, specifically PANC-1." (PMID 40675804, 2025). "Therefore, the findings of this study suggest that the disruption of PRMT1 oligomerization markedly inhibits the proliferation of pancreatic cancer cells, likely because of disturbance of PRMT1’s binding to RBPs enriched with RGG motifs." (PMID 40675804, 2025). "Furthermore, under stress conditions, such as DNA damage in pancreatic cancer cells, PRMT1 has been observed to bind and methylate with P14ARF." (PMID 38326807, 2024). "Taken together, we identified PRMT1 as a novel vulnerability that may be exploited therapeutically for the treatment of pancreatic cancer." (PMID 34330913, 2021). "Consequently, PRMT1 inhibition significantly sensitizes pancreatic cancer cells to GEM." (PMID 41256732, 2025). "Alternatively, combining low concentrations of PRMT1 or PRMT5 inhibitors is well tolerated in mice and can synergically reduce growth and promote apoptosis in pancreatic cancer and DLBCL cancer cells." (PMID 40823091, 2025).
pancreatic cancer (continued). "Combination of inhibitors of PRMT1 and PRMT5 has a synergistic cancer cell growth inhibition in pancreatic cancer and DLBCL cell lines and in pancreatic adenocarcinoma xenografts mouse models." (PMID 34522232, 2021). "The methylation of heat shock protein 70 by PRMT1 stabilized BCL2 mRNA and led to pancreatic cancer resistance to therapeutics." (PMID 34683150, 2021). "Downregulation of PRMT1 in PANC-1 and SW1990 cells reduces cell proliferation and invasion, yet overexpression of PRMT1 did not affect these events, which is explained by the high level of endogenous PRMT1, leading to saturation of the PRMT1 protein in pancreatic cancer cells." (PMID 38612768, 2024). "Notably, the restoration of PRMT1’s oligomeric forms, but not its dimeric or monomeric forms, can reverse this inhibition, indicating that the oligomeric state of PRMT1 is essential for sustaining pancreatic cancer cell proliferation." (PMID 40675804, 2025).
glioma (14 papers, 2018 to 2025). A benign or malignant brain and spinal cord tumor that arises from glial cells (astrocytes, oligodendrocytes, ependymal cells). "This was evident by an association of PRMT1 knockdown with suppression of glioma proliferation through cell cycle arrest in G1-S." (PMID 33440687, 2021). "Studies indicated that downregulating PRMT1 levels effectively arrested the cell cycle’s progression from the G1 to S phase in glioma cells exhibiting high PRMT1 levels, leading to the inhibition of proliferation and induction of apoptosis." (PMID 38326807, 2024). "PRMT1 has been found to be overexpressed in both human glioma tissue and cell lines compared to normal brain tissue." (PMID 38326807, 2024). "In their experiment, immunohistochemical staining of grade II gliomas showed a strong positive signal for PRMT1 as compared to a weak signal in normal brain tissue, with more than 76% of glioma samples having increased PRMT1 expression." (PMID 33440687, 2021). "For example, when PRMT1 was knocked down in glioma cells, the cells were arrested in G1/S with increased apoptosis." (PMID 30741995, 2019). "Furthermore, miR-494-3p overexpression and PRMT1 inhibition attenuated both glioma cell proliferation and metastasis." (PMID 33440687, 2021). "Moreover, PRMT1 knockdown in glioma cells significantly reduced the cell population in the S phase and significantly decreased proliferation rates." (PMID 33440687, 2021). "In addition, knockdown of PRMT1 can lead to the G1-S phase arrest of the cell cycle, proliferation inhibition and apoptosis induction in glioma cells in vitro and in xenografts, suggesting a potential oncogenic role for PRMT1 in gliomas." (PMID 36351894, 2022). "We demonstrate for the first time that PRMT1/H4R3me2a differentially regulates PTX3-driven ferritinophagic flux in IDH1 wild-type and mutant gliomas." (PMID 37476290, 2023). "In line with the results of syngeneic tumor models, higher cytotoxic T lymphocytes (CTLs) infiltration predicted better prognosis only when PRMT1 expression level was low in human cancer patients, including COAD, AML, lymphoma, and glioma." (PMID 37193698, 2023). "A diminished expression of PRMT1 (protein arginine methyltransferase 1) and its target asymmetric dimethyl H4R3 mark in IDH1-MT was concomitant with reduced PTX3 in IDH1-MT glioma cells and in patients." (PMID 37476290, 2023). "This correlation of PRMT1 and PTX3 with ferritinophagic markers is conserved in gliomas of diverse genetic landscape and shows prognostic value in IDH1 mutant glioma patients." (PMID 37476290, 2023). "Given that PRMT1 promotes radiotherapy resistance in glioma and was identified as a potential FOSL1 interactor, we hypothesized that FOSL1 interacts with PRMT1." (PMID 41423530, 2025). "PRMT1 mediated epigenetic modification H4R3me2a not only plays an essential role in PTX3 expression, but PRMT1 potentiated the ability of PTX3 to sensitize glioma cells to ferroptosis inducer." (PMID 37476290, 2023). "Interestingly, the expression levels of PRMT1, PRMT2, PRMT4, and PRMT6 in low-grade gliomas are significantly higher in IDH1/2 wild-type (WT) subgroups than the subgroups with the IDH1/2 mutations." (PMID 30382083, 2018). "In addition, the elevated expression of PRMT1, PRMT2, PRMT4, and PRMT6 predicts poor prognosis in glioma patients." (PMID 30382083, 2018). "Downregulated PRMT1 expression could hinder PTX3 transcription, resulting in escalated amalgamation between autophagosomes and lysosomes, along with an upsurge in ferritinophagy within glioma cells." (PMID 38326807, 2024). "PRMT1 promotes ferroptosis by suppressing key antioxidant systems, including solute carrier family 7-member 11 (SLC7A11), and its inhibition could provide dual therapeutic benefits—enhancing neuroprotection while improving treatment responses in conditions like gliomas." (PMID 40951640, 2025).
acute myeloid leukemia (12 papers, 2015 to 2025). Acute myeloid leukemia (AML) is a group of neoplasms arising from precursor cells committed to the myeloid cell-line differentiation. "Copious expression of protein arginine methyltransferase 1 (PRMT1) is associated with poor survival in many types of cancers, including acute myeloid leukemia." (PMID 40801789, 2025). "PRMT1 has already been proposed to be a potential epigenetic target in acute myeloid leukemia because it has been recognized to contribute to an aberrant epigenetic networks with KDM4C." (PMID 32517078, 2020). "show that PRMT1 is necessary but insufficient for acute myeloid leukemia induction by chimeric transcription factors, which also recruit KDM4C for epigenetic reprogramming." (PMID 26766589, 2016). "Gene expression data from AMKL patient samples shows a higher PRMT1 expression level than other types of acute myeloid leukemia." (PMID 26575292, 2015). "In addition to normal hematopoiesis, PRMT1 has a central position in leukemogenesis, and its roles have been characterized in acute myeloid leukemia (AML) and ALL." (PMID 36358861, 2022). "Furthermore, high expression of PRMT1 is correlated with poor survival rate in acute myeloid leukemia." (PMID 26575292, 2015). "In Fms‐like receptor tyrosine kinase 3 (FLT3)‐ITD mutant acute myeloid leukemia (AML), PRMT1 expression is markedly elevated." (PMID 41256732, 2025). "In the acute myeloblastic leukemia with maturation (M2) subtype of acute myeloid leukemia (AML), the in-flame fusion protein AML1-ETO (AE) isoform AE9a, a transcription factor, interacts with PRMT1 and recruits it to the AE9a promoter." (PMID 32859041, 2020). "Protein arginine methyltransferase 1 (PRMT1) can promote histone methylation in the promoter region of ACSL1, thus decreasing the level of lipid peroxidation and mediating ferroptosis resistance in acute myeloid leukemia (AML)." (PMID 38459004, 2024).